HCAR2 (hydroxycarboxylic acid receptor 2)
Description:
Acts as a high affinity receptor for both nicotinic acid (also known as niacin) and (D)-beta-hydroxybutyrate and mediates increased adiponectin secretion and decreased lipolysis through G(i)- protein-mediated inhibition of adenylyl cyclase. This pharmacological effect requires nicotinic acid doses that are much higher than those provided by a normal diet. Mediates nicotinic acid-induced apoptosis in mature neutrophils. Receptor activation by nicotinic acid results in reduced cAMP levels which may affect activity of cAMP-dependent protein kinase A and phosphorylation of target proteins, leading to neutrophil apoptosis. The rank order of potency for the displacement of nicotinic acid binding is 5-methyl pyrazole-3-carboxylic acid = pyridine-3-acetic acid > acifran > 5-methyl nicotinic acid = acipimox >> nicotinuric acid = nicotinamide.
Synonyms: GPR109A; HCA2; HM74A; NIACR1; PUMAG; Puma-g; HM74b
Tractability: Small molecule: a drug acting on it is in phase 2 or 3 trials; a structure with a bound ligand is known; a high-quality ligand is known; it belongs to a druggable protein family. Antibody: UniProt places it where antibodies can reach, with high confidence; its Gene Ontology location is reachable by antibodies, with high confidence; UniProt predicts a signal peptide or a membrane-spanning region. PROTAC: a small molecule that binds it is known.
Target class: Family A G protein-coupled receptor; Small molecule receptor (family A GPCR); Carboxylic acid receptor; Hydroxycarboxylic acid receptor; Membrane receptor
Gene: Protein-coding gene on chromosome 12 (122,701,293 to 122,703,357, reverse strand). Ensembl gene ENSG00000182782.
Subcellular location: Cell membrane
Subcellular location (Human Protein Atlas): Cell Junctions
Pathways (Reactome):
Signal Transduction: Class A/1 (Rhodopsin-like receptors); G alpha (i) signalling events; Hydroxycarboxylic acid-binding receptors
Gene Ontology:
Molecular function: protein binding; nicotinic acid receptor activity; G protein-coupled receptor activity
Biological process: neutrophil apoptotic process; positive regulation of neutrophil apoptotic process; G protein-coupled receptor signaling pathway; negative regulation of lipid catabolic process; positive regulation of adiponectin secretion
Cellular component: cell junction; plasma membrane; membrane
Genetic constraint (gnomAD): Loss-of-function variants: 0 observed, 0.25 expected, observed/expected ratio (o/e) 0, 90% interval 0 to 1.87. That is too few expected variants to judge how well the gene tolerates losing a copy. Missense variants: 346 observed, 443.3 expected, observed/expected ratio (o/e) 0.78, 90% interval 0.71 to 0.85. Synonymous variants: 156 observed, 171.87 expected, observed/expected ratio (o/e) 0.91, 90% interval 0.8 to 1.04.
Homologues: Orthologues: dog HCAR2 (86% identical), rat Hcar2 (82% identical), mouse Hcar2 (81% identical), guinea pig Hcar2 (77% identical), chimpanzee HCAR2 (72% identical). Paralogues in human: HCAR3 (95% identical), HCAR1 (49% identical), OXER1 (33% identical), GPR31 (29% identical), P2RY1 (24% identical), P2RY2 (23% identical), P2RY4 (23% identical), FFAR3 (20% identical), P2RY6 (20% identical), GPR42 (20% identical), SUCNR1 (20% identical), OXGR1 (19% identical), and 3 more.
Diseases named in the same sentence as HCAR2 in open-access papers:
HCAR2 is named in the same sentence as 118 diseases in open-access papers, as found by Europe PMC text mining. Sharing a sentence is not in itself a finding about the gene and the disease. The quoted sentences say what the papers report.
colitis (45 papers, 2015 to 2026). Inflammation of the colon. "Hanju Lee used the amino acid conjugation of IPA to prepare a colon-targeted indole propionic acid prodrug, which can effectively treat colitis in rats and enhance its anti-colitis activity through the synergistic delivery of the Hcar2 agonist 5-ANA." (PMID 40825672, 2025). "The activation of HCAR2 by butyrate has been demonstrated to protect against experimental colitis through suppressing the inflammatory response in immune cells and reinforcing the intestinal epithelial barrier." (PMID 38675452, 2024). "In this regard, acute DSS colitis in conventional C57BL/6 mice decreased the expression of Ffar2, Ffar3, and Hcar2, although this result was not confirmed by others." (PMID 38595917, 2024).
colon carcinoma (32 papers, 2011 to 2025). "It is important to note that, in a similar manner to that reported with FFAR2, the reduced expression of HCAR2 associated to colon cancer, difficult the potential beneficial effects of the activation of this receptor on tumor progression." (PMID 33113952, 2020). "Targeted deletion of the DNA methyltransferase 1 (DNMT1) induced HACR2 expression in colon cancer cell lines, suggesting that DNMT1 is responsible for the silencing of HCAR2 in colon cancer." (PMID 36432618, 2022). "We will also summarize the current knowledge of the implications of FFAR2 and HCAR2 on gut inflammation and colon cancer." (PMID 33897470, 2021). "The re-expression of HCAR2 in colon cancer cell lines and its activation by butyrate abolished NF-κB activation and induced apoptosis." (PMID 33897470, 2021). "The HCAR2 knockdown in mice accelerated the progression of colonic inflammation and colon cancer in multiple experimental model systems." (PMID 33897470, 2021). "An increased proliferation was detected in breast cancer cells after the knock down of HCAR2 while, the activation of HCAR2 by butyrate, induced the apoptosis of both colon cancer cells and breast cancer cells." (PMID 33113952, 2020). "Moreover, re-expression of HCAR2 by cDNA transfection in colon cancer lines induced apoptosis only in the presence of the ligand." (PMID 36432618, 2022).
Obesity (17 papers, 2011 to 2025). Accumulation of substantial excess body fat. "Moreover, HCAR2 activation protects against diet-induced obesity, and the metabolic effects of HCAR2 activation depend on diet." (PMID 40266880, 2025).
atherosclerosis (15 papers, 2013 to 2025). A disease characterized by the build-up of fatty material and calcium deposition in the arterial wall resulting in partial or complete occlusion of the arterial lumen. "Despite the usefulness of niacin in the treatment of atherosclerosis, patient compliance is greatly weakened by cutaneous flushing, caused by HCAR2 triggering the release of vasodilatory prostaglandins from Langerhans cells and keratinocytes." (PMID 37932263, 2023). "This suggests that activation of HCAR2 may be a potential therapeutic target for the treatment of diseases, such as atherosclerosis." (PMID 35309549, 2021).
dyslipidemia (11 papers, 2008 to 2025). "All of this was done under the assumption that HCAR2/GPR109A was in fact mediating the beneficial effect of niacin on dyslipidemia." (PMID 38918366, 2024). "Collectively, the structures presented here are expected to help in the design of ligands specific for HCAR2, leading to new drugs for the treatment of various diseases such as dyslipidemia and inflammation." (PMID 37932263, 2023). "Although many studies have indicated that HCAR2 is involved in various inflammatory disorders and dyslipidemia, the signaling mechanism of HCAR2 is still unknown at the molecular level." (PMID 37932263, 2023). "Thus, although this eliminated HCAR2/GPR109A as a drug target for the treatment of dyslipidemia, HCAR2 agonists do inhibit lipolysis, which potentially could be beneficial in e.g. diabetes." (PMID 38918366, 2024). "Therefore, HCAR2 should be a potential target for treating dyslipidemia and inflammatory diseases." (PMID 37743365, 2023). "The hydroxycarboxylic acid receptors (HCAR2 and HCAR3), also known as prototypical metabolite-sensing receptors, are key targets for treating dyslipidemia and metabolic disorders." (PMID 41359625, 2025). "HCAR2 shares the highest sequence similarity with HCAR3 in HCAR family, and is considered to be a molecular target for regulating dyslipidemia, activated by the endogenous ligand 3-hydroxybutyric acid." (PMID 41359625, 2025). "Acifran is a clinically-used drug that primarily targets both HCAR2 (EC50 = 10−5.7M) and HCAR3 (EC50 = 10−4.7M), to treat hypertriglyceridemia, type 2 diabetes, and metabolic syndrome." (PMID 41359625, 2025). "Compared to HCAR2, activation of HCAR3 can effectively control lipid levels while avoiding the side effect of flushing, making it a more promising therapeutic target for dyslipidemia treatment." (PMID 41359625, 2025). "Hydroxycarboxylic acid receptor 2 (HCAR2), a member of Class A G-protein-coupled receptor (GPCR) family, plays a pivotal role in anti-lipolytic and anti-inflammatory effects, establishing it as a significant therapeutic target for treating dyslipidemia and inflammatory diseases." (PMID 37743365, 2023). "Thus, although HCAR2 is no longer a valid drug target in dyslipidemia and likely not in diabetes either, the many HCAR2 ligands could potentially become useful as anti-inflammatory agents in the treatment of neuroinflammation and e.g. psoriasis." (PMID 38918366, 2024).
Parkinson disease (11 papers, 2014 to 2025). A progressive degenerative disorder of the central nervous system characterized by loss of dopamine producing neurons in the substantia nigra and the presence of Lewy bodies in the substantia nigra and locus coeruleus. "Emerging evidence has demonstrated the neuroprotective effects of niacin in Parkinson's disease, Alzheimer's disease, and ischemic stroke, primarily through HCAR2 activation." (PMID 41205412, 2025). "Indeed, previous studies show that ketosis (βHB) may evoke therapeutic effects in the treatment of Alzheimer’s disease, Parkinson’s disease and amyotrophic lateral sclerosis and enhance learning and memory through anti-inflammatory effects induced by HCAR2." (PMID 34206738, 2021).
Insulin resistance (10 papers, 2021 to 2025). Increased resistance towards insulin, that is, diminished effectiveness of insulin in reducing blood glucose levels. "At the same time, this paper further explored the molecular mechanism of 3HB decreasing insulin resistance level, which is by indirectly inhibiting the phosphorylation of PPARγ Ser273 site through HCAR2/Ca2+/cAMP/PKA/Raf1/ERK1/2/PPARγ signaling pathway." (PMID 37230992, 2023). "In combination, in vivo application of 1,3-BDO resulted in reduced FBG, insulin resistance level and tissue injury through HCAR2 in T2D mice, strongly supporting the potential therapeutic value of 3HB in T2D." (PMID 37230992, 2023). "Collectively, 3HB ameliorates insulin resistance in type 2 diabetic mice through a pathway of HCAR2/Ca2+/cAMP/PKA/Raf1/ERK1/2/PPARγ." (PMID 37230992, 2023). "Here we demonstrate that 3HB reduces fasting blood glucose level, improves glucose tolerance, and ameliorates insulin resistance in type 2 diabetic mice through hydroxycarboxylic acid receptor 2 (HCAR2)." (PMID 37230992, 2023). "3-Hydroxybutyrate, originating from the increased β-oxidation of free fatty acids, is found in higher concentrations in the plasma of T2DM patients and has been shown to ameliorate insulin resistance in T2DM mice through the HCAR2/Ca2+/cAMP/PKA/Raf1/ERK1/2/PPARγ pathway." (PMID 38184583, 2024). "Another study demonstrated that 3-hydroxybutyric acid could improve insulin resistance in diabetic mice by regulating hydroxycarboxylic acid receptor 2 (HCAR2)." (PMID 38962302, 2024). "The pathway of 3HB/HCAR2/Ca2+/cAMP/PKA/Raf1/ERK1/2/PPARγ might be the molecular mechanism by which 3HB ameliorates insulin resistance." (PMID 37230992, 2023). "Based on present in vitro results, we propose for the first time that 3HB regulates ERK1/2 activity via HCAR2/Ca2+/cAMP/PKA/Raf1, optimizing PPARγ function from the aspect of post-translational modification to reduce insulin resistance." (PMID 37230992, 2023).
Sepsis (9 papers, 2018 to 2025). Sepsis is defined as life-threatening organ dysfunction caused by a dysregulated host response to infection. "Besides, we observed the high level of expression of a hydroxycarboxylic acid receptor 2 (HCA2, FC= 13), which regulates lipolysis and at the same time reduces pro-inflammatory cytokines level in sepsis." (PMID 35531332, 2022).
breast cancer (8 papers, 2020 to 2023). A primary or metastatic malignant neoplasm involving the breast. "Though better known for regulating lipid metabolism in adipocytes, more recently, HCARs have been functionally associated with breast cancer proliferation/survival; HCAR2 has been described as a tumor suppressor and HCAR1 and HCAR3 as oncogenes." (PMID 34852802, 2021). "In contrast to data reported in colon and breast cancer, a recent study shows an increased proliferation of cells from glioblastoma by the activation of HCAR2 with butyrate." (PMID 33113952, 2020). "Thus, we sought to identify germline variants in HCAR1, HCAR2, and HCAR3 that could potentially be associated with breast cancer risk." (PMID 34852802, 2021). "Furthermore, in vivo studies have also demonstrated that the activation of HCAR2, with niacin and the commensal metabolite butyrate, suppresses colonic inflammation and carcinogenesis, while deletion of HCAR2 increased tumor incidence of spontaneous breast cancer in transgenic mice." (PMID 33113952, 2020).
colorectal cancer (7 papers, 2019 to 2025). A primary or metastatic malignant neoplasm that affects the colon or rectum. "3OHB was shown to exhibit anti-colorectal cancer activity through G protein-coupled 109A (GPR109A, also known as hydroxyl-carboxylic acid receptor 2; HCAR2) binding and activation, a tumor suppressor that inhibits lipolysis in the adipocytes." (PMID 39941898, 2025). "KD prevents and treats colorectal cancer by engaging the hydroxycarboxylic acid receptor 2 with β-hydroxybutyrate, subsequently activating the homeobox only protein signaling pathway to curb colorectal cancer cell proliferation and tumor development." (PMID 38594256, 2024). "The function of HCAR3 in CRC remains to be elucidated; however, a member of the same HCA receptor family with similar structure, named, HCAR2, which functions as a tumor suppressor gene, has been reported to have reduced expression levels in colorectal cancer cell lines." (PMID 31469863, 2019).
Alzheimer disease (6 papers, 2019 to 2025). A progressive, neurodegenerative disease characterized by loss of function and death of nerve cells in several areas of the brain leading to loss of cognitive function such as memory and language. "Similarly, HCAR2 activation has been shown to alleviate amyloid burden, prevent neuronal loss, and improve neurological function in Alzheimer's disease." (PMID 41205412, 2025).
multiple sclerosis (6 papers, 2020 to 2024). A progressive autoimmune disorder affecting the central nervous system resulting in demyelination. "The endogenous ketone body, BHB, also binds to the orthosteric pocket 14 as did monomethyl-fumarate (MMF), the HCAR2-activating metabolite of the multiple sclerosis drug, dimethyl-fumarate." (PMID 38918366, 2024). "Hcar2 is considered as a promising target may help to optimize multiple sclerosis (MS) therapies." (PMID 32599940, 2020). "HCAR2 is the receptor target through which the important ketone body, β-hydroxybutyrate (BHB), and the active metabolite of the multiple sclerosis drug dimethyl-fumarate mediate their anti-inflammatory actions." (PMID 38918366, 2024). "It is important to note that besides targeting Nrf2, dimethyl fumarate and its metabolite monomethyl fumarate are potent agonists for the hydroxycarboxylic acid receptor 2 (HCAR2) and are approved for the treatment of multiple sclerosis." (PMID 35204312, 2022).
gastric cancer (5 papers, 2025 to 2026). A primary or metastatic malignant neoplasm involving the stomach. "SCFAs bind specifically to Hydroxycarboxylic acid receptor 2(HCAR2, also called GPR109A), which selectively recognizes butyrate, inhibiting gastric cancer progression by enhancing CD8+ T-cell–mediated cytotoxicity, including that of CAR-Claudin 18.2+ CD8+ T cells." (PMID 40977700, 2025).
mastitis (5 papers, 2020 to 2025). Inflammation of breast tissue during lactation or postpartum due to an obstructed duct or infection. "Reduced migration and inflammation by activating HCAR2 may be positive as it may reduce excess inflammation and pathology associated with diseases like mastitis." (PMID 38444010, 2024). "Based on the results above, the potential alleviating effect of HCAR2 activation on S. aureus‐induced mastitis was explored." (PMID 39792800, 2025). "Next, Nia was used to activate HCAR2, and a mastitis model was established with S. aureus." (PMID 39792800, 2025). "The effect of HCAR2 agonists on immune cell migration is also inconsistent in vivo as BHBA infusions have reduced or not affected SCS in mastitis challenge models." (PMID 38444010, 2024).
diabetic retinopathy (4 papers, 2009 to 2026). "GPR109A/HCAR2 plays a significant role in regulating the blood–retinal barrier’s integrity and has therapeutic potential toward preventing and treating retinal diseases such as diabetic retinopathy, in which the compromised barrier function is of paramount importance." (PMID 37049975, 2023).
schizophrenia (4 papers, 2021 to 2025). A major psychotic disorder characterized by abnormalities in the perception or expression of reality. "GPR109A, also known as hydroxycarboxylic acid receptor 2 (HCAR2), is highly expressed in adipocytes, macrophages, and microglia in the brain areas associated with schizophrenia and AD." (PMID 39769034, 2024).
experimental autoimmune encephalomyelitis (3 papers, 2017 to 2025). An autoimmune demyelinating disease of the central nervous system that is produced experimentally in animals by the injection of homogenized brain or spinal cord in Freund's adjuvant. "Data from experimental autoimmune encephalomyelitis indicate effects of MMF on microglia to be mainly mediated through activation of hydroxycarboxylic acid receptor 2 (HCAR2), leading to a phenotypic change of microglia with neuroprotective properties." (PMID 28284222, 2017). "Notably, HCAR2 is required for the therapeutic efficacy of DMF in experimental autoimmune encephalomyelitis (EAE), a mouse model of MS, and in two mouse models of inflammatory skin diseases." (PMID 40266880, 2025). "Beside the upper mentioned pathways, the anti-inflammatory activity exerted by DMF is also reliant on its agonism of the hydroxycarboxylic acid receptor 2 (HCAR2), as demonstrated in vivo in a mouse model of experimental autoimmune encephalomyelitis (EAE)." (PMID 37745068, 2023). "Hcar2 reporter mice Hcar2mRFP indicate that diet and dimethyl fumarate (DMF) treatment have no marked effects on Hcar2 expression in peripheral immune cells of mice subjected to experimental autoimmune encephalomyelitis (EAE)." (PMID 40266880, 2025).
Hepatic steatosis (3 papers, 2019 to 2024). Steatosis is a term used to denote lipid accumulation within hepatocytes. "βOHB has been shown to activate the HCAR2/AMPK axis, leading to prevention of hepatic steatosis and the regulation of neutrophil‐mediated inflammation." (PMID 39126207, 2024).
ischemic stroke (3 papers, 2019 to 2025). A stroke disorder caused by obstruction of blood flow to the brain, due to thrombotic (local blood clot formation) or embolic (due to a blood clot or other material traveling from another site) event. "Specifically, activation of HCAR2 elicits a broad spectrum of microglia-mediated protective responses, leading to reduced infarct volume and attenuated brain injury in models of ischemic stroke." (PMID 41205412, 2025). "Previous studies have shown that HCAR2 expression in ischemic stroke models is restricted to microglia, with no expression in neurons or astrocytes." (PMID 41205412, 2025). "Meanwhile, the hydroxycarboxylic acid receptor 2 (HCAR2, GPR109A) may also mediate the neuroprotective effect of BHB in ischemic stroke." (PMID 39075604, 2024).